CD14 (CD14 molecule)
Diseases named in the same sentence as CD14 in open-access papers (continued):
Sharing a sentence is not in itself a finding about the gene and the disease.
Allergy (26 papers, 2012 to 2025). An allergy is an immune response or reaction to substances that are usually not harmful. "Early upregulation of TLR and CD14 expression likely leads to an increased ability to generate inhibitory signals for Th2 cell development and ultimately to reduced risk of allergic diseases." (PMID 36704753, 2022). "Several studies investigated the relationship between a polymorphism named C-159T in the CD14 gene promoter and allergic diseases." (PMID 30783593, 2019). "Several previous studies showed a positive association between CD14 gene polymorphism C-159T and allergic diseases, as well as serum CD14 levels." (PMID 30783593, 2019). "PCR-RFLP was done in patients and non-asthmatic control (n=220 in each) to characterize functional polymorphism, C(-159)T, of CD14, a positional candidate gene for allergy." (PMID 29937881, 2017). "As a result, the CD14 C-159 T promoter polymorphism was associated with serum CD14 levels as well as the phenotypes of patients with allergy." (PMID 24524443, 2014). "The association between cesarean delivery and AD was significantly modified by parental history of allergic diseases or risk-associated IL-13 (rs20541) and CD14 (rs2569190) genotypes." (PMID 24848505, 2014). "Earlier studies showed a positive correlation between CD14 gene polymorphism and allergic diseases." (PMID 41438035, 2025). "Consequently, CD14 plays a substantial role in allergic diseases and may become one of their etiological causes." (PMID 37286630, 2023). "Moreover, there is a relationship between CD14 C-159T gene polymorphism and some allergic diseases." (PMID 30783593, 2019). "A genome-wide search for vulnerable loci modifying allergic reactions has identified CD14 as a significant candidate gene in allergic reactions." (PMID 37286630, 2023). "For example, single nucleotide polymorphisms (SNPs) in CD14, TLR4, and TLR2 genes have been correlated with the development of allergy sensitization and symptoms of allergy in children." (PMID 36704753, 2022). "Accordingly, CD14 plays an important role in allergic and atopic diseases, which can be one of the etiological factors for allergic diseases." (PMID 30783593, 2019). "We then tested if Gal1 reversed the ability of IL-10 expression in allergy mouse-derived CD14+ cells." (PMID 28086216, 2017). "Although patient 7 responded to adalimumab and iTNFα+ CD14+ cells increased accordingly after two injections, treatment was discontinued after the third injection due to allergy." (PMID 25037855, 2014). "The inverse correlation between LCT and CD14 expression in the ileum is striking and requires further investigation, especially in the context of irritable bowel syndrome, small intestinal bacterial overgrowth, and cow’s milk protein allergy." (PMID 33920682, 2021). "Lactoferrin (80 kDa), monocyte differentiation antigen CD14 (56 kDa), polymeric immunoglobulin receptor (83 kDa), and lactadherin (~50 kDa) are some examples of proteins often mentioned in relation to the allergy-protective effect of raw cow’s milk, that fall within the molecular weight range." (PMID 32438725, 2020). "Previous studies have revealed four genetic polymorphisms in human TLR2, TLR4, and CD14, such as TLR2 rs1898830, TLR2 rs4696480, TLR4 rs4986790 and CD14 rs2569190, which play a role in the pathogenic mechanism of allergic diseases and the protection mechanism of maternal exposure to farming." (PMID 30140427, 2018). "The allergy mouse-derived CD14+ cells were treated with Gal1 in the culture for 48 h." (PMID 28086216, 2017). "We have previously reported that exposure to labor may reveal differences in the innate and adaptive immune phenotype among infants who subsequently develop allergic disease, and that increased innate immune (CD14+ monocyte) responsiveness at birth predicts subsequent allergic disease." (PMID 36211431, 2022).
Allergy (continued). "However, IL-13 and CD14 genes are good candidate genes in terms of allergic susceptibility and innate immunity since several studies have shown that IL-13 rs1295685 and CD14 rs20541 play an important role in the development of allergic diseases in Korean children." (PMID 24848505, 2014). "Gene polymorphisms of TLR2-15607 (rs1898830 GG SNP) and TLR2-16934 (rs4696480 AA SNP), but not TLR4 rs4986790 and CD14 rs2569190, were involved in the protective role of maternal exposure to farming against allergy in the offspring." (PMID 30140427, 2018). "Finally we showed that human CD14+CD16+ intermediate monocytes, which are found in increased numbers in patients with allergies and bronchial asthma, expressed high levels of miR-124 and exhibited other properties of M2-like cells." (PMID 24358127, 2013). "Elevated soluble CD14 in patients with non-IgE allergy could be connected to increased intestinal permeability and point out the importance in the immune response outcome associated with microbial translocation as we have previously shown in patients with IBD." (PMID 41438035, 2025). "Notably, soluble CD14, a protein in human milk that may be protective against the development of food allergies, was not different between the allergy groups in our study (uncorrected p = 0.43)." (PMID 36311719, 2022).
endotoxemia (26 papers, 2010 to 2025). "This study showed that MCT administration prevented CD14-activation dependent endotoxemia mediated by LPS, a model consensually associated to obesity and metabolic syndrome." (PMID 27187452, 2016). "While there was a 4-fold increase in CD14 expression, Sphk-1 only increased by 2-fold indicating that additional signaling components are likely to be involved in the hyperinflammatory state associated with endotoxemia in the aged." (PMID 23817990, 2013). "A previous animal study showed that the M1 to M2 (M1/M2) macrophage ratio had a positive correlation with plasma LPS binding protein levels and TLR4 and CD14 mRNA levels, supporting the role of endotoxemia in the induction of liver inflammation." (PMID 39200311, 2024). "Studies have shown that using IC14 (a recombinant anti-CD14 monoclonal antibody) can decrease the response to lipopolysaccharide in models of endotoxemia in both animals and humans." (PMID 39606629, 2024). "A study using chronic low-dose LPS infusion as an endotoxemia model showed that metabolic endotoxemia induced by diet increases proinflammatory cytokine in adipose tissue as well as liver and skeletal muscle in a CD14-dependent manner." (PMID 38037591, 2023). "In endotoxemia, after LPS binds to CD14 on the surface of monocytes and phagocytoses, the TLR-4/CD14 complex is cleaved into sCD14 (the water-soluble form of CD14)." (PMID 34335269, 2021). "LPS-binding protein (LBP) and soluble CD14 (sCD14) dimerize to bind to circulating LPS, and increased levels in the plasma are indicative of higher circulating LPS levels and endotoxemia, making these viable proxy measures for LPS." (PMID 31817899, 2019). "Even though leucocyte count and endotoxemia increased with the severity of disease in this study, soluble CD14, as a marker for monocyte activation, decreased in severe alcoholic hepatitis underlining the dysregulation of the immune response." (PMID 30800122, 2019). "In accordance, treatment with anti-CD14 (IC14) during human endotoxemia strongly inhibited LPS-induced proinflammatory cytokine release, whereas the release of anti-inflammatory cytokines such as soluble TNF receptor type I and IL-1Ra was only delayed." (PMID 30944694, 2019). "In vitro study further supports hepatocyte-specific CD14 transcriptional activities after LPS treatment, highlighting a possible role of hepatocyte-derived CD14 in endotoxemia." (PMID 22511970, 2012). "Our data and those of others have indicated that hepatocytes express CD14 under basal conditions and that hepatic CD14 mRNA and protein levels are markedly increased during endotoxemia." (PMID 22511970, 2012). "In our BDL rat model, we confirmed that endotoxemia and hepatocyte CD14 production occurred after ligation." (PMID 21172039, 2010). "Models of endotoxemia are of scientific importance in the evaluation of specific biological mechanisms and pathways, such as the immune response to the prototypical stimuli of specific Toll-like receptor pathways, such as LPS and CD14/MD2/TLR417." (PMID 36522357, 2022). "In addition, it was shown that genetically obese ob/ob mice display a lower endotoxemia and caecal LPS content following the inactivation of CD14, a cell receptor involved in inflammation." (PMID 27187452, 2016). "Although mouse and human hepatocytes have also shown increased expression of CD14 during endotoxemia, CD14 production in the liver and the subsequent effects on endotoxin-induced liver injury during obstructive jaundice remain unclear." (PMID 22511970, 2012). "Hepatocytes are the major source of most acute-phase proteins; therefore, hepatocytes might be expected to express CD14, which is upregulated during endotoxemia induced by cholestasis." (PMID 21172039, 2010).
endotoxemia (continued). "Acute endotoxemia caused a long-lasting increase in mRNA expression of inflammatory markers such as TLR-4, CD14 and serum amyloid A (SAA) in the adipose tissue, which may represent the key factors connecting inflammation to increased susceptibility to weight gain and impaired glucose homeostasis." (PMID 35335996, 2022). "Binding of LPS with LBP is the first step in activating the CD14:TLR4 pathogen recognition pathway, and even subclinical amounts of LPS in circulation are considered evidence of systemic endotoxemia." (PMID 40427905, 2025). "Results of the present study are consistent with this proposed signaling pathway, whereby concomitant increases in Sphk-1, CD14 and TNF-α were identified in hepatic tissues of animals subjected to endotoxemia." (PMID 23817990, 2013). "However, results of the current study collectively indicate that the hyperinflammatory state previously observed during endotoxemia in the aged may, in part, be due to the increase in Kupffer cell CD14 expression, leading to increased Sphk-1 and subsequent increases in TNF-α." (PMID 23817990, 2013). "The expression of SLA-DR was the lowest on the CD14+CD163− monocytes and it did not change significantly during endotoxemia regardless of the iNO + hydrocortisone treatment." (PMID 35566768, 2022).
Stroke (26 papers, 2008 to 2025). Sudden impairment of blood flow to a part of the brain due to occlusion or rupture of an artery to the brain. "Enhanced CD14 expression on monocytes has been linked to the acquisition of a tolerance to endotoxin exposure, characterized by an inability to secrete proinflammatory cytokines, a phenotype observed in stroke." (PMID 33205448, 2021). "A recent study also reported higher levels of CD14+ microparticles to be associated with stroke severity indicating that CD14 may be part of the post-stroke inflammatory process." (PMID 32084157, 2020). "Moreover, the sequential activation of transcription factor regulatory networks in neutrophils during stroke progression is delineated, many of which are unique to the CD14+ population and underlie their acquisition of chemotaxis and granule release capacities." (PMID 39930981, 2025). "Blood sample analysis two days post-stroke identified six significantly upregulated tRFs and highlighted CD14+ monocytes as central players in the cholinergic inflammatory reflex, linking specific tRFs to immune responses following stroke." (PMID 41415912, 2025). "Along with Fos and Jun, Cebpb, Ets2, Egr1, and Junb were enriched in Neut_Gngt2 and Neut_Cd14, particularly after stroke." (PMID 39930981, 2025). "We also evaluated the relative expression of Cd14 in neutrophils from the brain, CBM, FBM, and blood, and confirmed high expression of Cd14 in the ischemic brain, with the post‐stroke increase in Cd14 expression being most significant in brain." (PMID 39930981, 2025). "Stroke was also the main effect in increasing the anti-inflammatory A2 astrocyte markers: Cd14 and Clcf1, whereas Tgm1 was only increased in HT + Stroke vs HT + Sham (P < 0.05)." (PMID 38886874, 2024). "Our research indicates that the decreased susceptibility to stroke is associated with an increase in the expression of CD40 in monocytes, particularly in CD14+ CD16+ and CD14+ CD16- monocytes, with the latter two demonstrating the most compelling evidence." (PMID 38887301, 2024). "Conversely, a decreased susceptibility to stroke was associated with increased CD40 expression on monocytes, particularly on CD14+ CD16+ and CD14+ CD16- monocytes, with the latter two showing the most compelling evidence." (PMID 38887301, 2024). "While this study focused on the post-stroke alterations to MEVs, and the involvement of CD14 and MHC-II in the response to ischemic stress, future studies should harness recent advancements in transcriptomics to identify disease-specific candidate MEV markers." (PMID 36721258, 2023). "In experimental stroke models, CD14 expression is increased 7 and 28 days post-stroke, and has been documented in post-stroke human microglia within the lesion site." (PMID 36721258, 2023). "We report a significant increase in circulating TMEM119+/CD14+ EVs 28-days post-stroke in comparison to baseline levels and saline-injected rats, which correlated weakly with stroke volume." (PMID 36721258, 2023). "To confirm the presence of TMEM119+/CD14+ EVs in plasma we performed co-immunoprecipitation using TMEM119+ EVs isolated from 28-day post-stroke rat plasma." (PMID 36721258, 2023). "Intravenous administration of mononuclear UCB cells, including CD14+ monocytes, 48 h post-stroke led to a significant reduction in infarct size and promoted functional recovery in contrast to CD14+-monocyte-depleted controls." (PMID 34072923, 2021). "An increased percentage of CD163+/CD16+ and CD163+/CD14++ events occurred 24 and 48 h after a stroke compared to the controls." (PMID 34201498, 2021). "Conversely, the percentage of CD80+/CD16+ events was unaffected in patients; meanwhile, the percentage of CD80+/CD14+ events significantly increased only 24 h after stroke." (PMID 34201498, 2021).
Stroke (continued). "At 8 weeks post-stroke, the top 10 genes were Cd44 (degree = 14), Fcgr2b (degree = 13), C1qb (degree = 13), Cd74 (degree = 12), C1qc (degree = 11), Cd14 (degree = 10), C4a (degree = 10), Spp1 (degree = 10), RT1-A2 (degree = 9), and Itgb2 (degree = 9)." (PMID 31888302, 2019). "Using single‐cell sequencing in a murine stroke model (p‐MCAO), three stroke‐specific subpopulations are identified: disease inflammatory macrophage (DIM), disease‐associated microglia (DAM), and CD14+ neutrophils (Neut_Cd14)." (PMID 39930981, 2025). "Taken together, we hypothesize that the previously uncharacterized Neut_Cd14 might play a key role in stroke immunity." (PMID 39930981, 2025). "Furthermore, transcription factor analysis of the Neut_Cd14 subpopulation revealed that, within 1 h of stroke onset, specific transcription factors related to Neut_Cd14 differentiation were expressed in the affected skull." (PMID 39930981, 2025). "This increase may be due to both the upregulation of CD14 expression by microglia as well as local proliferation of microglia that occurs post-stroke, both of which would results in an increase in CD14+ MEV release." (PMID 36721258, 2023). "TMEM119+/CD14+ EVs were weakly correlated with stroke volume suggesting that the extent of tissue damage may be reflected by circulating microglial-EVs, however this finding requires further validation with a larger sample size." (PMID 36721258, 2023). "Thus, we detected a significant increase in the percentage of CD163+/CD16+ and CD163+/CD14++ events 24 and 48 h after stroke, compared to healthy individuals." (PMID 34201498, 2021). "This study demonstrates that inflammatory gene SNPs are associated with early-onset ischemic stroke among African-American women (IL6) and that cigarette smoking may modulate stroke risk through a gene-environment interaction (IL6 and CD14)." (PMID 18727828, 2008). "This study demonstrates that inflammatory gene SNPs may be associated with early-onset ischemic stroke among African-American women (IL6) and that cigarette smoking may modulate stroke risk through a gene-environment interaction (IL6 and CD14)." (PMID 18727828, 2008). "However, it did identify two polymorphisms that appear to influence stroke risk via a gene-environment interaction with cigarette smoking, IL6 rs2069830 and CD-14 rs2569190." (PMID 18727828, 2008). "Clinical studies have shown that the CD14+ CD16-and CD14+ CD16+ subpopulations of monocytes increase significantly between 0 and 16 days after the onset of IS, with an increase in the CD14+ CD16-subpopulation being closely associated with tissue damage in the acute and subacute phases of stroke." (PMID 36762188, 2022). "In stroke, CD14++ CD16− DR+ monocytes were also higher in patients with systemic axonal injury, early worsening, poor prognosis, and early mortality, indicating that monitoring of monocyte subtypes may represent a useful tool for predicting clinical course and prognosis in stroke patients." (PMID 33408685, 2020). "CD14highCD16+ intermediate Mo may be involved in CNS tissue damage in progressing infarction, while CD14 dimCD16high non-classical monocytes were shown to be relevant to stroke-associated infection." (PMID 23936327, 2013). "In the plasma assays of both TMEM119+/CD14+ and TMEM119+/ MHC-II+ EVs, dual-labelled EVs were increased at 28 days post-stroke, but insignificantly at 7-days post-stroke." (PMID 36721258, 2023). "Conversely, the percentage of CD80+/CD16+ events was unaffected after stroke, whereas the percentage of CD80+/CD14++ events was significantly increased 24 h after the insult as compared to CT." (PMID 34201498, 2021). "LAMA2, MLL4 and PLXDC2 are specifically expressed in (pre-)diabetic sera; CD99 is expressed in the sera of both healthy and (pre-)diabetic patients; and CD14, CLU and SAA2 are expressed in the sera of healthy, (pre-)diabetic and stroke subjects." (PMID 33995275, 2021).